PLD2 (phospholipase D2)
Description:
Function as phospholipase selective for phosphatidylcholine. May have a role in signal-induced cytoskeletal regulation and/or endocytosis (By similarity).
Synonyms: PLD1C
Tractability: Small molecule: a structure with a bound ligand is known; a high-quality ligand is known; it belongs to a druggable protein family. Antibody: its Gene Ontology location is reachable by antibodies, with high confidence; UniProt places it where antibodies can reach, with medium confidence. PROTAC: ubiquitination databases record sites on it; a small molecule that binds it is known.
Target class: Enzyme; Hydrolase
Chemical probes: ML-298, ML272, ML300, ML395, VU0364739 (high quality)
Gene: Protein-coding gene on chromosome 17 (4,807,117 to 4,823,434, forward strand). Ensembl gene ENSG00000129219.
Subcellular location: Cell membrane
Pathways (Reactome):
Metabolism: Synthesis of PA; Synthesis of PG
Signal Transduction: RAC1 GTPase cycle; RAC2 GTPase cycle
Immune System: Role of phospholipids in phagocytosis
Gene Ontology:
Molecular function: protein binding; phospholipase D activity; catalytic activity; phosphatidylinositol binding
Biological process: cytoskeleton organization; Fc-gamma receptor signaling pathway involved in phagocytosis; phosphatidic acid biosynthetic process; regulation of vesicle-mediated transport; small GTPase-mediated signal transduction; synaptic vesicle recycling; intracellular signal transduction
Cellular component: plasma membrane; cytoplasmic vesicle; endoplasmic reticulum membrane; brush border membrane; presynapse
Genetic constraint (gnomAD): Loss-of-function variants: 88 observed, 112.58 expected, observed/expected ratio (o/e) 0.78, 90% interval 0.66 to 0.93. The upper end of that interval is the gene's LOEUF score, 0.93, which puts it in group 3 of 6, group 1 being the genes least tolerant of losing a copy. Missense variants: 1,134 observed, 1,236.8 expected, observed/expected ratio (o/e) 0.92, 90% interval 0.87 to 0.96. Synonymous variants: 488 observed, 493.05 expected, observed/expected ratio (o/e) 0.99, 90% interval 0.92 to 1.07.
Homologues: Orthologues: chimpanzee PLD2 (99% identical), macaque PLD2 (97% identical), pig PLD2 (94% identical), dog PLD2 (92% identical), guinea pig PLD2 (91% identical), rat Pld2 (90% identical), mouse Pld2 (90% identical), tropical clawed frog pld2 (62% identical), zebrafish pld2 (58% identical), rabbit PLD2 (57% identical), Drosophila melanogaster Pld (46% identical), Caenorhabditis elegans pld-1 (44% identical). Paralogues in human: PLD1 (56% identical).
Diseases named in the same sentence as PLD2 in open-access papers:
PLD2 is named in the same sentence as 82 diseases in open-access papers, as found by Europe PMC text mining. Sharing a sentence is not in itself a finding about the gene and the disease. The quoted sentences say what the papers report.
breast carcinoma (24 papers, 2010 to 2024). "Overall survival analyses suggested that high expression levels of stearoyl-CoA desaturase-1 (SCD1) and PLD2 in breast cancer patients were both associated with metastasis-related morbid outcomes." (PMID 33832505, 2021). "The PLD2 point mutation has been found in breast cancer cells, and PLD2 overexpression confers a survival signal attributed to an increase in basal mTOR activity." (PMID 20711340, 2010). "Moreover, PLD2 point mutations have been detected in patients with breast cancer, and cell invasion of highly metastatic cancer cells is dependent on PLD2." (PMID 32998768, 2020). "The PLD2 point mutation has also been found in breast cancer." (PMID 20711340, 2010). "The elevated expression and activity of PLD, especially PLD2, have been detected in various human cancer tissues and cells, including breast cancer." (PMID 38612766, 2024). "The increased PLD2 activity indicates breast cancer cells resist the traditional mTOR inhibitor rapamycin." (PMID 37978168, 2023). "PLD2 activity increases in various tumors, including breast cancer, colon cancer, gastric cancer, and renal cell carcinoma." (PMID 37978168, 2023). "Data from Hatton and colleagues indicated that EGFR expression levels in human breast cancer cells were related to PLD2 expression and its enzymatic reaction product PA." (PMID 33832505, 2021). "In contrast, PLD2 phosphorylates Janus Kinase3 (JAK3) has been reported to promote cell invasion in breast cancer." (PMID 35127525, 2021). "The combination treatment of SAHA with PLD2 inhibitor significantly enhances cell death in breast cancer cells." (PMID 32998768, 2020). "Combination of these HDAC inhibitors with PLD2 inhibitor showed accumulative effect on inducing apoptosis of MDA-MB 2312 breast cancer cells." (PMID 32998768, 2020). "In this study, we performed Western blot, q-PCR, and promoter assay to examine the expression of HDAC inhibitor-induced phospholipase D2 (PLD2) in MDA-MB231and MDA-MB435 breast cancer cells." (PMID 32998768, 2020). "SAHA upregulates expression of PLD2 via protein kinase C-ζ in breast cancer cells and increases the enzymatic activity of PLD." (PMID 32998768, 2020). "Both PLD1 and PLD2 selective inhibitors were found to enhance the radiosensitivity of breast cancer cells." (PMID 28083512, 2016). "Genetically enforced overexpression of PLD1 or PLD2 in a human breast cancer xenograft model led to primary tumor initiation and increased metastasis." (PMID 28083512, 2016). "Phospholipase D-2 (PLD2) has a key role in breast cancer formation and metastasis formation with PLD small inhibitors reducing primary tumor growth." (PMID 27851813, 2016). "In a previous study, we have provided in vivo evidence that the PLD2 isoform is fundamental to human breast cancer progression." (PMID 27851813, 2016). "Stable transduction of either PLD1 or PLD2 overexpression in a much less aggressive human breast cancer cell line boosted tumor growth in a SCID model." (PMID 27851813, 2016). "In our lab, we have recently demonstrated that PLD2 plays a role in breast cancer invasion and tumorigenesis in vivo." (PMID 24103483, 2014). "Conversely, when PLD2 was overexpressed in a low invasive breast cancer cell line and xenotransplated into SCID mice, more substantial breast tumors arose." (PMID 24103483, 2014). "PLD2 was stably silenced in highly invasive breast cancer cells and led to tumors derived from these cells being only mildly invasive in SCID mice." (PMID 24103483, 2014). "We determined the mechanism of mammary tumor cell invasion and metastasis seen following PLD2 overexpression as being mediated by PA, Grb2 and Rac2." (PMID 24103483, 2014).
breast carcinoma (continued). "MDA-MB-231 breast cancer cells with high levels of PLD2 activity invade Matrigel in in vitro experiments, however, breast cancer cells with very low PLD2 activity, such as MCF-7, are less invasive." (PMID 27713341, 2010). "Y is an inhibitory site and its phosphorylation explains the low PLD2 activity that exists in low-invasive MCF-7 breast cancer cells." (PMID 20623096, 2010). "Furthermore, our recent study highlighted a phospholipase D2 (PLD2)/mTOR-dependent signaling pathway in OA-induced breast cancer cell migration." (PMID 37373069, 2023). "Upregulation of PLD2 was observed in multidrug-resistant colon and breast cancer cells, suggesting that PC-PLD could provide a survival signal involved in therapy resistance." (PMID 35250970, 2022). "Recent breast cancer models in mice have also indicated increased FES expression as linked to tumor aggressiveness, macrophage infiltration, and involvement in the JAK3‐Fes‐PLD2 signaling pathway." (PMID 34189853, 2021). "Interestingly, while PLD2 was found to impact exosome secretion by governing ILV biogenesis in a different breast carcinoma cell line, our data rather suggest that PLD1 controls exosome biogenesis in 4T1 cells." (PMID 33404012, 2021). "Moreover, activation of the PLD2-Fes-Jak3 signaling pathway can accelerate the proliferation and invasion of breast cancer cells." (PMID 32256211, 2020). "Since phospholipase D (PLD2 isoform) gene expression is upregulated in breast cancer cells and PARN is downregulated, we examined whether a signaling connection existed between these two enzymes." (PMID 28011629, 2017). "When treated with isoform-specific PLD inhibitors, the viability of MDA-MB-231 breast cancer cells grown in the regular culture medium that contained high glucose (25 mM) was not significantly altered by either the PLD1 inhibitor (PLD1i) or PLD2 inhibitor (PLD2i)." (PMID 27809301, 2016). "Additionally, knockdown of PLD2 in an aggressive cell line of human breast cancer using short-hairpin RNA (shRNA) specific for PLD2 decreased primary mammary tumor growth and lung metastases in a xenotransplanted SCID mouse model." (PMID 27851813, 2016). "As the current study was performed in breast cancer cell lines, it suggests a key role for PLD2 in maintaining the levels of EGFR and could be used as a target for modulating its expression." (PMID 26493292, 2015). "Protein kinase Czeta activation by PLD2-PX domain promotes survival of breast cancer cells." (PMID 24103483, 2014). "Phosphatidic acid, a product of PLD activity, prevented apoptosis promoted by cotreatment with SAHA and PLD2 inhibitor, suggesting that SAHA-induced PLD2 expression and subsequent activation of PLD2 might confers resistance of breast cancer cells to HDAC inhibitor." (PMID 32998768, 2020). "There are several studies about breast cancer using the CAM assay approach; the anticancer drug effects of phospholipase D2 (PLD2) and histone deacetylase (HDAC) inhibitors of the palladium complex BTC2 have been shown." (PMID 36980588, 2023). "Given that PLD2 is mandatory for mTOR and S6K signaling in MDA-MB-468 breast cancer cells, it can be concluded that this pathway was most likely involved in MDA-NEO and MDA-HER2 cell migration since both cell lines were derived from MDA-MB-468 cells." (PMID 33832505, 2021). "The present study demonstrates that PLD2 is upregulated by HDAC inhibitor and PLD1 inhibition increases HDAC inhibitor-induced apoptosis of breast cancer cells." (PMID 32998768, 2020). "In the present study, we show that expression of PLD2 is upregulated by HDAC inhibitors, and confers resistance to HDAC inhibitors in breast cancer cells." (PMID 32998768, 2020).
breast carcinoma (continued). "HDAC inhibitors such as trichostatin (TSA), suberoylanilide hydroxamic acid (SAHA, also known as Vorinostat), and apicidin upregulated expressions of PLD2 in MDA-MB 231 and MDA-MB435 breast cancer cells as determined by q-PCR." (PMID 32998768, 2020). "In summary, we report for the first time the involvement of a phospholipase (PLD2) and PA in mediating PARN-induced eukaryotic mRNA decay and the crosstalk between the two enzymes that is deregulated in breast cancer cells." (PMID 28011629, 2017). "Surprisingly, in the MCF-7 breast cancer cells, both PARN and PLD2 protein co-overexpression augmented the expression of each of these proteins in parallel." (PMID 28011629, 2017). "By using normal and breast cancer cell lines that were mock-treated or that overexpressed PARN and/or PLD2, we defined the relationship between PARN and PLD2." (PMID 28011629, 2017). "The mechanism proposed in the present study mainly considered breast cancer cells, such as MDA-MB-231 cells in which PLD2 was overexpressed." (PMID 26493292, 2015). "PLD inhibitors clearly inhibit the invasion of breast cancer cells in culture and, similarly, inhibition of PLD1 and PLD2 by triptolide decreases cell proliferation in MDA-MD-231 cells." (PMID 24103483, 2014). "Therefore, increased PLD2 expression and PA levels in MDA-MB-231 breast cancer cells were directly correlated with higher EGFR expression levels." (PMID 33832505, 2021). "However, Diaz-Aragon and colleagues concluded from their data that both PLD1 and PLD2 were involved in the linoleic acid-induced migration and invasion as well as sphere formation of MDA-MB-231 human breast cancer cells." (PMID 33832505, 2021). "Combined treatment of SAHA and PLD2 inhibitor showed approximately 10% inhibition on MCF-10A cell viability, while the inhibition rate of combined treatment on MDA-MB231 breast cancer cells is approximately 60%, indicating that the combinational effect is more specific for cancer cells." (PMID 32998768, 2020). "Data from this present study indicates that although PLD2 gene expression in breast cancer was not affected by small-molecule inhibitor treatment, its protein expression was reduced after such treatment, which also negatively impacted PLD2 lipase activity." (PMID 27851813, 2016). "In breast cancer MCF-7 cells, the enzyme phospholipase D2 (PLD2) was required for the formation of intraluminal vesicles within a fraction of the MVBs, while inhibition of PLD2 activity attenuated only the secretion of syntenin-containing exosomes in these cells." (PMID 30242145, 2018). "Co-expression of both PARN and PLD2 mimicked this pattern in non-cancerous cells (COS-7 fibroblasts) but, surprisingly, not in breast cancer MCF-7 cells, where PARN switches from inhibition to activation of PLD2 gene and protein expression." (PMID 28011629, 2017). "We determined the endogenous gene expression of both PARN and PLD2 in COS-7 fibroblasts, used as a non-cancerous ‘normal’ cell line, as well as in the breast cancer cell line MCF-7." (PMID 28011629, 2017). "However, it cannot be ruled out that other PLD-dependent pathways, such as the PLD2-Grb2 complex or MAPK signaling, might also be involved in the migration of MDA-NEO and MDA-HER2 breast cancer cells." (PMID 33832505, 2021).
colorectal cancer (12 papers, 2010 to 2024). A primary or metastatic malignant neoplasm that affects the colon or rectum. "We previously showed that the PLD2 gene, encoding phospholipase D2, is overexpressed in colorectal cancer and induces stemness in cancer cells through communication with the tumor microenvironment." (PMID 38403587, 2024). "Elevated expression of PLD1 and PLD2 has been reported in colorectal cancer tissues; in particular, PLD2 expression level and its association with clinicopathological features have recently been investigated in colorectal carcinoma." (PMID 20711340, 2010). "One interesting report indicates that a polymorphism in the PLD2 gene is associated with increased risk of colorectal cancer." (PMID 20711340, 2010). "Findings from a recent study showed a significant association of PLD2 expression level with tumor size (P<0.05) and survival of patients with colorectal carcinoma (P<0.05)." (PMID 20711340, 2010). "A polymorphism of the PLD2 gene has recently been associated with prevalence of colorectal carcinoma." (PMID 20711340, 2010). "For examples, the C1814T (Thr577Ile) polymorphism in the human PLD2 gene is associated with the prevalence of colorectal cancer, and a naturally-occurring variant of human PLD2 in which Gly901 in the COOH-terminal region is replaced by the charged amino acid Asp is catalytically inactive." (PMID 23675264, 2012). "In addition, a PLD2 gene polymorphism was shown to be prevalent in colorectal cancer in a Japanese case study, where it was demonstrated that a C → T mutation resulting in Thr → Ile is associated with colorectal cancer." (PMID 24103483, 2014). "As little information exists on how PLD2 function precisely effects tumor initiation and progression in CRC, it is of great importance to reveal a novel role of PLD2 in transformation and progression in colorectal cancer and provide the potential mechanisms." (PMID 38706911, 2024). "Accordingly, it is of great importance to study how PLD2 functioned in tumor transformation and progression in colorectal cancer patients in China." (PMID 38706911, 2024). "In this regard, we previously showed that exosomes from PLD2-overexpressing colorectal cancer cells induced senescence in stromal fibroblasts, which, in turn, induced WNT pathway activation and increased stemness in tumor cells." (PMID 38403587, 2024). "We investigated the expression of PLD2 and its biological functions and clinical implications in human colorectal cancer." (PMID 38706911, 2024). "Increased PLD2 expression and activity is observed in human colorectal cancer when compared to normal mucosa." (PMID 24103483, 2014). "Expression levels of PLD2 correlate significantly with tumor size and survival of patients with colorectal carcinoma." (PMID 20711340, 2010). "Since we previously connected PLD2 overexpression with tumor stemness in colorectal cancer, we analyzed whether alterations in the chromatin accessibility landscape of OC cells induced by hypoxia and PLD2 could result in increased expression of stemness genes." (PMID 38403587, 2024). "Therefore, exploring the interaction mechanisms between EGFR and PLD2 in colorectal cancer liver metastasis is of great significance for cancer biology research and the formulation of clinical treatment strategies." (PMID 39581873, 2024). "Elevated expression of PLD1 and PLD2 has been reported in colorectal cancer tissues." (PMID 20711340, 2010). "Additionally, the overexpression of phospholipase D2 (PLD2) in colorectal cancer cells induces fibroblast senescence in the microenvironment and SASP secretion related to phospholipid acid, activating the Wnt pathway to promote their stemness characteristics (described in more detail below)." (PMID 38540708, 2024).
colorectal cancer (continued). "Since PLD2 expression is increased under hypoxic conditions in colon cancer cells and is involved in tumor stemness through communication with the microenvironment in colorectal cancer, we investigated whether hypoxia could increase the expression of PLD2 in OC." (PMID 38403587, 2024). "Moreover, several key genes strongly associated with reprogramming of cellular metabolism, invasion and metastatic spreading in human colorectal carcinoma were significantly differentially expressed in PLD2 knockdown and overexpression CRC cell lines compared to control cell lines." (PMID 38706911, 2024). "Furthermore, inhibition and genetic knockdown of PLD2 significantly induced autophagy in HT29 and HCT116 colorectal cancer cells." (PMID 31327962, 2019). "To further confirm whether endogenous SIRT1 and PLD isozymes can form a natural complex in colorectal cancer cells (HT119 and HT29 cells) and A549 lung adenocarcinoma cells, which express both endogenous PLD1 and PLD2, we performed coimmunoprecipitation assays." (PMID 34471223, 2021).